RPS2 (ribosomal protein S2)
Description:
Component of the ribosome, a large ribonucleoprotein complex responsible for the synthesis of proteins in the cell. The small ribosomal subunit (SSU) binds messenger RNAs (mRNAs) and translates the encoded message by selecting cognate aminoacyl-transfer RNA (tRNA) molecules. The large subunit (LSU) contains the ribosomal catalytic site termed the peptidyl transferase center (PTC), which catalyzes the formation of peptide bonds, thereby polymerizing the amino acids delivered by tRNAs into a polypeptide chain. The nascent polypeptides leave the ribosome through a tunnel in the LSU and interact with protein factors that function in enzymatic processing, targeting, and the membrane insertion of nascent chains at the exit of the ribosomal tunnel. Plays a role in the assembly and function of the 40S ribosomal subunit (By similarity). Mutations in this protein affects the control of translational fidelity (By similarity). Involved in nucleolar processing of pre-18S ribosomal RNA and ribosome assembly (By similarity).
Synonyms: LLREP3; S2; uS5
Tractability: Small molecule: an approved drug acts on it; a structure with a bound ligand is known; a high-quality ligand is known. PROTAC: UniProt records ubiquitination sites on it; ubiquitination databases record sites on it; its protein half-life has been measured; a small molecule that binds it is known. Other modalities: a drug acting on it is in phase 2 or 3 trials.
Target class: Other cytosolic protein
Gene: Protein-coding gene on chromosome 16 (1,962,050 to 1,965,510, reverse strand). Ensembl gene ENSG00000140988.
Subcellular location: Cytoplasm; Nucleus, nucleolus
Subcellular location (Human Protein Atlas): Cytosol; Endoplasmic reticulum
Pathways (Reactome):
Metabolism of proteins: Eukaryotic Translation Termination; Formation of a pool of free 40S subunits; Formation of the ternary complex, and subsequently, the 43S complex; GTP hydrolysis and joining of the 60S ribosomal subunit; L13a-mediated translational silencing of Ceruloplasmin expression; PELO:HBS1L and ABCE1 dissociate a ribosome on a non-stop mRNA; Peptide chain elongation; Protein methylation; Ribosomal scanning and start codon recognition; SRP-dependent cotranslational protein targeting to membrane; Translation initiation complex formation; ZNF598 and the Ribosome-associated Quality Trigger (RQT) complex dissociate a ribosome stalled on a no-go mRNA
Metabolism of RNA: Major pathway of rRNA processing in the nucleolus and cytosol; Nonsense Mediated Decay (NMD) enhanced by the Exon Junction Complex (EJC); Nonsense Mediated Decay (NMD) independent of the Exon Junction Complex (EJC); rRNA modification in the nucleus and cytosol
Disease: SARS-CoV-1 modulates host translation machinery; SARS-CoV-2 modulates host translation machinery; Viral mRNA Translation
Developmental Biology: M-decay: degradation of maternal mRNAs by maternally stored factors; Regulation of expression of SLITs and ROBOs
Cellular responses to stimuli: Response of EIF2AK4 (GCN2) to amino acid deficiency
Chromatin organization: RMTs methylate histone arginines
Metabolism: Selenocysteine synthesis
Gene Ontology:
Molecular function: cadherin binding; enzyme binding; fibroblast growth factor binding; mRNA binding; protein binding; RNA binding; structural constituent of ribosome
Biological process: positive regulation of ubiquitin-protein transferase activity; cytoplasmic translation; translation
Cellular component: cytoplasm; cytosolic ribosome; cytosolic small ribosomal subunit; extracellular exosome; focal adhesion; membrane; nucleolus; nucleoplasm; nucleus; cytosol; ribosome; small ribosomal subunit
Genetic constraint (gnomAD): Loss-of-function variants: 5 observed, 21.34 expected, observed/expected ratio (o/e) 0.23, 90% interval 0.12 to 0.49. The synonymous counts are far from expectation, so gnomAD's model fits this gene poorly and the ratio says little. Missense variants: 200 observed, 338.7 expected, observed/expected ratio (o/e) 0.59, 90% interval 0.52 to 0.66. Synonymous variants: 172 observed, 136.02 expected, observed/expected ratio (o/e) 1.26, 90% interval 1.12 to 1.43.
Homologues: Orthologues: macaque RPS2 (100% identical), mouse Rps2 (99% identical), tropical clawed frog rps2 (92% identical), zebrafish rps2 (90% identical), Drosophila melanogaster RpS2 (74% identical), Caenorhabditis elegans rps-2 (68% identical). Paralogues in human: MRPS5 (26% identical).
Diseases named in the same sentence as RPS2 in open-access papers:
RPS2 is named in the same sentence as 45 diseases in open-access papers, as found by Europe PMC text mining. Sharing a sentence is not in itself a finding about the gene and the disease. The quoted sentences say what the papers report.
prostate carcinoma (9 papers, 2009 to 2025). A carcinoma that arises from epithelial cells of the prostate gland. "It has been reported that RPS2 promotes tumors, and it is overexpressed in human prostate cancer, breast cancer, squamous cell carcinoma, and hepatocellular carcinoma." (PMID 35212607, 2022). "It was reported that RPS2 ribosomal protein was over expressed in malignant prostate cancer cell lines and in archived tumor specimens." (PMID 36140189, 2022). "Rps2, a 32 kDa ribosomal protein, is over expressed in prostate cancer and promotes malignancy of human prostate PC-3ML cells in the severe combined immunodeficiency (SCID) tumor modeling studies." (PMID 29190643, 2017). "To date, uS5 (rpS2) was reported to be a therapeutic target for the eradication of prostate cancer in preclinical tumor modeling studies." (PMID 28085118, 2017). "rpS2 was reported to be a therapeutic targeting for the eradication of prostate cancer in preclinical tumor modeling studies." (PMID 27924828, 2016). "We have previously reported that RPS2, a 33 Kda ribosomal protein was over expressed in malignant prostate cancer cell lines and in archived tumor specimens." (PMID 19138403, 2009). "Previously, we have cloned a mutant variant of the RPS2 ribosomal protein, termed PCADM-1, and shown that RPS2 was over expressed in malignant prostate cell lines and in human prostate cancer (PCa)." (PMID 19138403, 2009). "Earlier immunolabeling studies with polyclonal antibodies had revealed that the RPS2 antigen was over-expressed in 100% of prostate cancer luminal epithelial cells (n = 20 prostates examined)." (PMID 19138403, 2009). "Western blotting and RT-PCR have been used to measure and compare the levels of expression of RPS2 in a variety of malignant prostate cancer cell lines, plus normal and benign cells lines." (PMID 19138403, 2009). "In sum, we have shown for the first time that therapeutic targeting of RPS2 is an excellent approach for the eradication of prostate cancer in preclinical tumor modeling studies." (PMID 19138403, 2009). "For example, we have previously reported that RPS2, a 33 Kda ribosomal protein was over expressed in malignant prostate cancer cell lines and in archived tumor specimens." (PMID 19138403, 2009). "Recently, the RPS2 protein was reported to be a novel therapeutic target in prostate cancer." (PMID 22709827, 2012). "We have, therefore, focused on studies designed to test whether RPS2 over expression in prostate cancer cell lines is essential for cell survival." (PMID 19138403, 2009). "Likewise, the normal RPS2 gene was found to be over-expressed by malignant prostate lines (i.e. PC-3 ML and LNCaP cells), and by early stage prostate cancer cell lines (HGPIN, CPTX-1532)." (PMID 19138403, 2009). "The implication is that targeting RPS2 in prostate cancer might be an excellent therapeutic strategy." (PMID 19138403, 2009). "The data suggest that PCADM-1 and/or RPS2 might be novel bio-markers and excellent prognostic indicators for human prostate cancer." (PMID 19138403, 2009). "The RPS2 and OASL were considered to be a potential therapeutic target in prostate cancer and lung cancer." (PMID 33133154, 2020).
Autoimmunity (3 papers, 2018 to 2024). The occurrence of an immune reaction against the organism's own cells or tissues. "CPR30 is allelic to CPR1 and involved in complex-mediated stability control of plant NLR proteins (SNC1 and RPS2) in regulating their protein levels and prevent autoimmunity." (PMID 39656686, 2024). "These super DETs that are heat shock proteins may assist SGT1B in the formation of SCF E3 ubiquitin ligase complexes that target the immune receptors SNC1, RPS2 and RPS4 for degradation to regulate receptor levels and avoid autoimmunity." (PMID 30283484, 2018).
neuroblastoma (3 papers, 2022 to 2025). Neuroblastoma (NB) is the most common solid, extracranial childhood tumor. "PEG10 silencing inhibited neuroblastoma cell proliferation and invasion via the miR-449a/RPS2 axis." (PMID 35212607, 2022).
prostate tumor (3 papers, 2009 to 2022). "Overexpression of RPS2 has been linked with the survival of prostate tumors, whereas suppression of RPS2 or RPS3a resulted in apoptosis." (PMID 28966624, 2017). "Like S3a, our data suggested that over expression of RPS2 was associated with prostate tumor formation and key for tumor cell survival." (PMID 19138403, 2009). "In addition, miRNAs target RPS2, such as pre-let-7a binding to RPS2 could block expression of let-7a, thereby promoting prostate tumor growth." (PMID 35212607, 2022).
breast carcinoma (2 papers, 2022 to 2024).
colon cancer (2 papers, 2018 to 2022). "The correlation between CD4+ T cells and RPS14 (correlation = −0.5) was the highest in colon cancer while CD8+ T and RPS2 (correlation = −0.53) was the highest in rectal cancer." (PMID 35127345, 2022).
colorectal cancer (2 papers, 2009 to 2021). A primary or metastatic malignant neoplasm that affects the colon or rectum. "Several of the identified antigens are currently discussed as biomarkers including HSP1, MAZ, and RPS2 that are up-regulated in colorectal cancer, acute myeloid leukaemia, and astrocytoma, respectively." (PMID 19284601, 2009).
embryonal tumors (2 papers, 2023 to 2024). "In embryonal tumors, the topmost DE genes included many ribosome-associated genes like RPS2, RPLP1, and RPL13A as well as histone H3.3 related genes like H3F3A and H3F3B." (PMID 36865335, 2023).
hepatocellular carcinoma (2 papers, 2012 to 2022). A malignant tumor that arises from hepatocytes. "HEPATOCELLULAR CANCER: Increased expression of ribosomal protein S2 was found in mouse hepatocellular carcinoma (HCC) samples and in mouse livers after partial hepatectomy." (PMID 22709827, 2012).
leukemia (2 papers, 2009 to 2024). A malignant (clonal) hematologic disorder, involving hematopoietic stem cells and characterized by the presence of primitive or atypical myeloid or lymphoid cells in the bone marrow and the blood. "Treatment of Cpd_DC60 also suppressed the expression of RPL8 and RPS2, resembling the impact caused by SGF29 depletion in leukemia." (PMID 38394203, 2024). "Finally, RPS2 was shown by our lab to specifically bind a classical 'break point cluster region' sequence found in leukemia, implicating RPS2 as a DNA binding protein." (PMID 19138403, 2009). "Last, CRISPR depletion of Rpl8 and Rps2 inhibited the MLL-AF9 cell survival, resembling the effect of sgSgf29 on these leukemia cells." (PMID 38394203, 2024). "Notably, ectopic expression of RPL8 and RPS2 was insufficient to reverse the impact triggered by sgSGF29, suggesting additional factors downstream of SGF29 are likely required for leukemia maintenance." (PMID 38394203, 2024).
squamous cell carcinoma (2 papers, 2017 to 2022). A carcinoma arising from squamous epithelial cells. "Previous studies have found that Rps2 is overexpressed in human squamous cell carcinoma and breast tumor samples." (PMID 29190643, 2017).
COVID-19 (1 paper, 2025). A disease caused by infection with severe acute respiratory syndrome coronavirus 2. "KEGG analysis of all proteins in this cluster showed that they were mainly enriched in “Protein export,” “Coronavirus disease-COVID-19” and “Ribosome” pathways, after ranking the interacting proteins involved in these pathways, RPS2 was found to have the highest score." (PMID 41312345, 2025).
Infertility (1 paper, 2023). "The topological analysis of the WGCN of the testis transcriptional cell atlas highlighted important somatic genes in this network, including RPL39, RPL10, RPL13A, FTH1, RPS2, and RPL18A, which have been reported to be associated with infertility." (PMID 38012716, 2023).
influenza (1 paper, 2025). An acute viral infection of the respiratory tract, occurring in isolated cases, in epidemics, or in pandemics; it is caused by serologically different strains of viruses (influenzaviruses) designated A, B, and C, has a 3-day incubation period, and usually lasts for 3 to 10 days. "For influenza, discriminatory ribosomal genes included RPL7A, RPL13, RPL18, RPL23A, RPLP2, RPS2, and RPS4X." (PMID 41020849, 2025).
male infertility (1 paper, 2023). The inability of the male to effect fertilization of an ovum after a specified period of unprotected intercourse. "We also identified key somatic cell genes, including RPL39, RPL10, RPL13A, FTH1, RPS2, and RPL18A, which were highly influential in the weighted gene co-expression network of the testis transcriptional cell atlas and have been previously implicated in male infertility." (PMID 38012716, 2023).
melanoma (1 paper, 2020). A malignant, usually aggressive tumor composed of atypical, neoplastic melanocytes. "We recommend the use of a combined geometric mean of the expression levels of CASC3 and RPS2 for normalization of gene expression in melanoma cell lines." (PMID 31567589, 2020). "We recommend using a geometric mean of the expression of CLTA, MRPL19 and ACTB for normalization of gene expression in melanomas and a geometric mean of the expression of CASC3 and RPS2 for normalization of gene expression in melanoma cell lines." (PMID 31567589, 2020). "CASC3 and RPS2 also were evaluated as reference genes in yet two other melanoma cell lines and a number of other cell lines of origin different from melanoma (breast and placenta), and they were found to be robustly expressed in all cases." (PMID 31567589, 2020). "For studies of gene expression in melanoma cell lines; we identified CASC3 and RPS2 as robust reference genes over 13 different melanoma cells lines." (PMID 31567589, 2020). "In melanoma cell lines, a geometric mean of the reference genes CASC3 and RPS2 is estimated to be the most optimal NF according to geNorm." (PMID 31567589, 2020). "Thus, based on the results from the two algorithms the most optimal NF for melanoma cell lines can be calculated as a geometric mean of reference genes CASC3 and RPS2." (PMID 31567589, 2020).
Obesity (1 paper, 2021). Accumulation of substantial excess body fat. "Furthermore, the results illustrate that the mRNA expression levels of PCM1, SIRT1, EEF1G, PTEN and RPS2 were significantly decreased in the obesity compared with the control group." (PMID 34248836, 2021).
ovarian carcinoma (1 paper, 2024). A malignant neoplasm originating from the surface ovarian epithelium. "Notably, expression levels of RPS6, RPL12, CTNNB1, RPL7, RPS2, and CALM3 did not have any impact on the survival of ovarian cancer patients." (PMID 39309198, 2024).
rectal cancer (1 paper, 2022). A primary or metastatic malignant neoplasm that affects the rectum. "Furthermore, only RPS2 was upregulated in tumor compared to normal in rectal cancer of TCGA, which may due to the different molecular expression characteristics between CTCs and solid tumor cells." (PMID 35127345, 2022). "In rectal cancer, the highest correlation was found between CD8+ T and RPS2 (correlation = −0.53) and macrophage and RPS2 (correlation = −0.46)." (PMID 35127345, 2022).
retinitis pigmentosa (1 paper, 2022). Retinitis pigmentosa (RP) is an inherited retinal dystrophy leading to progressive loss of the photoreceptors and retinal pigment epithelium and resulting in blindness usually after several decades. "Finally, it is reported that RPS2 is inclusive of retinitis pigmentosa and heart valve dysplasia." (PMID 35075370, 2022).